CCL5 (C-C motif chemokine ligand 5)
Diseases named in the same sentence as CCL5 in open-access papers (continued):
Sharing a sentence is not in itself a finding about the gene and the disease.
glioblastoma (41 papers, 2010 to 2026). The most malignant astrocytic tumor (WHO grade IV). "CCL5 can act as a prognostic measure of glioblastoma patient survival, as CCL5 overexpression is associated with shorter overall survival." (PMID 33803414, 2021). "High expression of CCR5 and CCL5 in glioblastoma tissue is associated with poor prognosis of patients." (PMID 33923334, 2021). "CCL5 produced by low-grade tumor-associated microglia of the glioblastoma TME is responsible for maintaining neurofibromatosis type 1 (NF1) mouse optic glioma growth in vivo." (PMID 32630699, 2020). "Leveraging Nf1-deficient murine M-GBM models, we further demonstrate that Ccl5 shRNA-mediated knockdown increases glioblastoma cell apoptosis in vitro, as well as extends mouse glioblastoma survival in vivo." (PMID 28380429, 2017). "Finally, we addressed glioblastoma intra-tumor heterogeneity, due to stromal cells’ interactions by analyzing CCL5/CCR5 expression in tumor-associated macrophages and tumor-associated MSCs." (PMID 32545571, 2020). "This strategy enabled the virus to selectively direct the production of CCL5 to EGFR-expressing tumor cells within the glioblastoma microenvironment." (PMID 40867316, 2025). "Glioblastoma cell-derived EVs upregulated the expression of the pro-tumor genes in microglia cells, including the CXCL1/10, CCL2/CCL5, and IL-6, and downregulated immune response-associated genes, such as IL-16, IL-23, and IL-2740." (PMID 39781357, 2025). "The communication of GBM with immunocompetent cells follows two pathways, either (a) external activation of glioblastoma cells expressing CCR5 or (b) GBM cells expressing CCL5 activate stromal cells." (PMID 33923334, 2021). "Overexpression of the CCR5 ligand CCL5 (RANTES) in glioblastoma completes a potential autocrine activation loop to promote tumor proliferation and invasion." (PMID 33923334, 2021). "GSCs isolated from patient glioblastoma tumours secrete CCL5 into the supernatant and induce the migration of primary human microglia." (PMID 33803414, 2021). "Whereas in glioblastoma, high levels of CCL5/CCR5 enable an autocrine chemokine activation, resulting in increased tumor cell proliferation and invasion that is becoming independent of stromal cells." (PMID 32545571, 2020). "The in vitro invasion of patients-derived primary glioblastoma cells and glioblastoma stem cells was dependent on CCL5-induced CCR5 signaling and is strongly inhibited by the small molecule CCR5 antagonist maraviroc." (PMID 32545571, 2020). "Glioblastoma cells secrete CCL5 and express CCR5, which is also expressed by stromal cells of the TME." (PMID 32630699, 2020). "Critical roles of CCL5/CCR5 axis in regulating glioblastoma proliferation and invasion was demonstrated in brain tumors." (PMID 32456359, 2020). "In support of this model, we detected CCL5 and CCR5 in MSC monocultures and glioblastoma-associated MSC in tissue sections." (PMID 32545571, 2020). "Yet the key relevance of autocrine vs. paracrine CCL5/CCR5 singling axis in glioblastoma progression remains poorly understood and was therefore addressed in this study." (PMID 32545571, 2020). "Glioblastoma is a highly invasive tumor, in which CCL5 expression correlates with shorter patient survival." (PMID 32545571, 2020). "In summary, we demonstrate, for the first time, that CCL5 functions in an autocrine growth-promoting circuit, and establish a new receptor responsible for CCL5 function in mesenchymal glioblastoma cells." (PMID 28380429, 2017). "Therefore, we believed that in glioblastoma, the overexpression of CCL5 enhances the NKκB and IFNγ signaling pathway of tumor-infiltrating T cells, leading to their exhaustion." (PMID 41155216, 2025). "Consequently, treatment with OV-Cmab-CCL5 resulted in a significant reduction in tumor size and improved survival rates in mouse models of glioblastoma." (PMID 40867316, 2025).
glioblastoma (continued). "PCs isolated from human glioblastoma biopsies were found to produce CCL5, which could promote tumor resistance to temozolomide in primary glioblastoma cells." (PMID 37569686, 2023). "Apart from its immunomodulatory effects, CCL5 also directly affects glioblastoma tumour cells." (PMID 33803414, 2021). "There are also reports on the role of CCL5 in activating the mammalian target of rapamycin (mTOR) pathway, which has been shown to be critical for the maintenance of GSCs and the survival of mesenchymal glioblastoma tumour cells." (PMID 33803414, 2021). "CCL5 has been identified to be overexpressed in glioblastoma." (PMID 33803414, 2021). "SG may be used as a new complementary therapy of the same medicine and food, acting on the target CCL5 and playing an anti-glioblastoma effect." (PMID 34987553, 2021). "Increased invasion of glioblastoma cells could also be activated by CCL5/CCR5 signaling the migratory downstream pathways through αvβ3 integrin, PI3K/Akt kinases, NF-κB pathways, and proteases such as matrix metalloproteases (MMPs)." (PMID 32545571, 2020). "Tumor-associated macrophages represent about 40% of all cells in a glioblastoma specimen and microglia-mediated immunosuppression may involve CCL5/CCR5 via CCR5 signaling on macrophages to induce their activation and polarization." (PMID 32545571, 2020). "Here, we hypothesized a correlation between CCR5 and CCL5 protein levels in individual patient-derived glioblastoma tissues, with respect to CCR5 vs. CCL5 distribution." (PMID 32545571, 2020). "In glioblastoma, CCL5 upregulation has been correlated with recurrence in post-treatment tumors." (PMID 30990165, 2019). "The OV-Cmab-CCL5 was targeted to EGFR+ glioblastoma (GBM) tumor cells, significantly enhancing the migration and activation of natural killer cells, macrophages, and T cells." (PMID 40295404, 2025). "This may be occurring in vivo, as dormant GSCs reside in glioblastoma tissue niches and are presumably activated in a paracrine cross-talk by stromal cells, infiltrating the niche to migrate out of the niches, expressing CCL5 and CCR5." (PMID 32545571, 2020). "We are still far from understanding complex multiple interactions under in vivo conditions, however, by categorically studying bilateral ligand and receptor expressions by selected cell types, their specific mechanisms in CCL5/CCR5 signaling in glioblastoma may be elucidated." (PMID 32545571, 2020). "One study found that knocking down APOE in glioblastoma cells altered cytokine secretion (increased IL-6/IL-12/TNF-α and decreased CCL5/TGF-β) and reduced the proportion of M2 macrophages in a co-culture system." (PMID 40745073, 2026). "A 25-plex ELISA, measuring 23 of the 34 cytokines we consider here, showed that ZIKV infection only significantly increased CXCL10 and CCL5 secretion and decreased CCL2 secretion from adult glioblastoma cells." (PMID 40240536, 2025). "Corroborating our findings, three key pro-inflammatory cytokines with known anti-tumoural functions (IL-6, CCL5 and CXCL10) are also significantly secreted by ZIKV-infected glioblastoma cells." (PMID 40240536, 2025). "OV-Cmab-CCL5 is redirected to EGFR - positive glioblastoma (GBM) cells and facilitates continuous production of the cytokine CCL5 in the tumor microenvironment." (PMID 40697381, 2025). "The results indicated that the source of CCL5, CCL7, and CXCL1 in our experimental system was mainly MSCs, while CXCL16 was predominantly secreted by glioblastoma U251 cells." (PMID 39272976, 2024). "Since maraviroc significantly inhibited CCL5 and MSC cells induced GBM and GSC invasion, we proposed targeting the CCL5–CCR5 signaling axis as novel glioblastoma therapeutics." (PMID 33923334, 2021). "Within the glioblastoma TME, CCL5 produced by GAMs, mesenchymal stem cells (MSCs) and tumour cells signals through CCR1, CCR5 and CD44." (PMID 33803414, 2021).
glioblastoma (continued). "In conclusion, we have demonstrated the heterogeneous tissue/cellular distribution and subcellular expression of CCL5 and CCR5 in glioblastoma." (PMID 32545571, 2020). "CCL5 silencing reduces mesenchymal GBM cell survival in vitro, and increases mouse glioblastoma survival in vivo (tumor xenograft)." (PMID 32630699, 2020). "As the recurrences are known to be more aggressive, we suggest that CCL5 and CCR5 autocrine signaling is playing a significant role in glioblastoma progression." (PMID 32545571, 2020). "Here, we demonstrated that CCR5-expressing primary glioblastoma cells and glioblastoma stem cells (GSC) invasion, when enhanced by recombinant CCL5, was also significantly inhibited by adding maraviroc." (PMID 32545571, 2020). "Using immunohistochemistry, we identified CCL5 and CCR5 in a series of glioblastoma samples and cells, including glioblastoma stem cells." (PMID 32545571, 2020). "Surface expression of US28 in glioblastoma cells was observed and tumor cells were invasive in response to CCL5/RANTES." (PMID 29601503, 2018). "Consistent with its role as a glioblastoma growth regulator, Ccl5 knockdown in M-GBM cells reduces M-GBM cell survival in vitro, and increases mouse glioblastoma survival in vivo." (PMID 28380429, 2017). "We demonstrated that these glioblastoma cells were put into relatively cytokine "rich" environment produced by AT-MSC containing IL-1β, IL-1ra, IL-2, IL-4, IL-6, IL-8, TNF-α, IFN-γ, CCL5, CCL26, CXCL10, PDGF-bb." (PMID 20509882, 2010). "This may also have a double effect of interrupting the pericyte secretion of CCL5, which acts on CCR5 on glioblastoma cells, inducing resistance to TMZ by promoting DNA damage repair mechanisms." (PMID 34771532, 2021). "CCL5 was not expressed in glioblastoma stem cells, suggesting a need for paracrine activation of CCR5 signaling by the stromal cells." (PMID 33923334, 2021). "However, exploring the gene expression distribution of CCR5 and CCL5 among different genetic subtypes, we found the highest levels of both genes in the CL-glioblastoma subtype and the lowest in MES-glioblastoma subtype." (PMID 32545571, 2020). "As the role of CCL5/CCR5 expression in glioblastoma stem cell expansion had not been investigated, we investigated the role of CCR5 expression in tumor invasiveness." (PMID 32545571, 2020). "To further investigate the cellular origin of CCL5 and CCR5 in glioblastoma tissues, using IHC we screened for the expression of CCL5 and CCR5 in primary differentiated glioblastoma cells and glioblastoma stem cells (GSCs) that were cultured from patients’ tumors." (PMID 32545571, 2020). "Moreover, higher CCL5 and CCR5 were detected in secondary, recurrent glioblastoma as compared to the primary glioblastoma." (PMID 32545571, 2020). "Using the CCR5 antagonist, maraviroc, we have shown CCL5 and CCR5 drive primary glioblastoma (GB) cells and glioblastoma stem cells (GSCs) invasion and their interactions with stromal MSCs and can be used as repositioned drug for novel clinical trials in glioblastoma." (PMID 32545571, 2020). "Moreover, CCL5 further enhances the US28-mediated invasiveness of glioma cells and primary glioblastoma cultures, showing the relevance of ligand-induced signaling in US28-associated pathologies." (PMID 25805993, 2015). "In addition, the study reported that APOE knockdown in glioblastoma cells attenuated tumor migration/invasion while reprogramming cytokine secretion—elevating antitumor cytokines (IL-6/IL-12/TNF-α) and suppressing immunosuppressive CCL5/TGF-β." (PMID 41390817, 2025). "Furthermore, in all types tested, i.e., oligodendroglioma WHO grade II, anaplastic oligoastrocytoma WHO grade III, and glioblastoma WHO grade IV, expression level of CCRL2 correlated significantly in a similar way with the expression of its potential ligands, CCL2 and CCL5." (PMID 32456359, 2020).
glioblastoma (continued). "We detected high level US28-specific release of Ca++ in response to CCL5/RANTES or CX3CL1/Fractalkine in primary smooth muscle cells but not in the glioblastoma derived cells, although it is currently unclear why US28 would fail to induce this response in the glioblastoma cells." (PMID 23209769, 2012). "Moreover, in MES-glioblastoma, the autocrine CCL5-dependent activation loop has also been proven by adding exogenous CCL5, and because no further activation was achieved, it was concluded that CCL5 promotes survival and proliferation of the cells in a cell-autonomous manner." (PMID 32545571, 2020). "Secondly, we detected higher CCL5 and CCR5 proteins in glioblastoma tissues and cells than in non-malignant brain tissues and normal astrocytes." (PMID 32545571, 2020). "We found that US28 does activate the PLC-β signaling pathway in a constitutive manner in the glioblastoma cells, but fails to respond to extracellular ligands such as CCL5/RANTES and CX3CL1/Fractalkine to promote the release of intracellular calcium." (PMID 23209769, 2012). "In the three glioblastoma stem cells (GSCs) spheroids, high CCR5 protein expression was seen, but CCL5 could not be detected even using more sensitive detection by immunofluorescence." (PMID 32545571, 2020). "Furthermore, both CCL5 and CX3CL1 promote US28-dependent Ca2+ mobilization in a PTX-insensitive manner in HCMV-infected smooth muscle cells, but not in U373 glioblastoma cells." (PMID 25805993, 2015).
Arthritis (40 papers, 2006 to 2026). Inflammation of a joint. "It was shown that human synovial fibroblasts were susceptible and permissive to CHIKV ex vivo experimental infection, and single-cell analysis evidenced a strong upregulation of arthritis-associated genes RANTES/CCL5 and IL-8 from infected cells." (PMID 35632709, 2022). "In addition, administration of a neutralizing anti-CCL2 antibody reduced ankle swelling in the rat CIA model, CCL3-deficient mice exhibited milder arthritis induced by an anti-type II collagen mAb and treatment with polyclonal anti-CCL5 antibody ameliorated adjuvant-induced arthritis in rats." (PMID 30053130, 2018). "Genes commonly associated with T cell activation, such as LAG3, CCL5, ITM2A, CCR5, and CD2, were highly expressed in SF, in comparison to PB T cells of arthritis patients." (PMID 38254179, 2024). "This is supported by the fact that blockade of CCL5 in inflamed glands halts Sjögren-like disease and that blockade of CCL5 by CD8 T cells halts experimental arthritis." (PMID 35720379, 2022). "For example, CCL5 is mainly involved in the migration of leukocytes, and the use of anti-CCL5 antibodies can reduce the pathological manifestations of arthritis in the CIA mouse model." (PMID 35874704, 2022). "CHIKV susceptibility and in vitro single-cell correlation studies showed that the arthritis-related genes RANTES / CCL5 and IL-8 significantly upregulate in infected human synovial fibroblasts." (PMID 36699921, 2022). "CD8 T cells through production of CCL5 have been shown to regulate inflammation in experimental models of arthritis." (PMID 35720379, 2022). "CCL5, a T-cell and monocyte chemoattractant, plays an important role in the development of adjuvant-induced arthritis." (PMID 16805906, 2006). "MIP-1α/CCL3 and RANTES/CCL5 demonstrated high constitutive expression on macrophages in adjuvant-induced arthritis, which correlated with the expression of CCR2 (MCP-1/CCL2 receptor) by macrophages and was proved to play an important role in maintaining inflammatory changes in the joints." (PMID 36293292, 2022). "Inhibition of CCL5 release by these cells inhibited arthritis flares in a murine model of RA." (PMID 35720379, 2022). "Met-CCL5 is a CCL5 receptor antagonist, which is used extensively to block the pathogenic effects of CCL5 and attenuate CCR5-mediated inflammatory processes during the development of arthritis, colitis, airway inflammation, allograft rejection and chronic liver diseases." (PMID 25182681, 2014). "In an equine IL-1β-induced carpal synovitis model, CCL2, CCL3, CCL5, and CCL11 were identified as sensitive biomarkers during the early stages of joint inflammation (synovitis), exhibiting temporal variations in their response." (PMID 40496923, 2025). "Using the flow cytometry-based, predesigned Human Chemokine CBA Kit, we detected higher levels of CCL2, CCL3, CCL4, CCL5, CXCL9, and CXCL10 in arthritis than in CTRL plasma." (PMID 28619088, 2017). "This study focuses upon three chemokines, namely CCL5, CXCL10 and CCL3, which are potential novel therapeutic targets in arthritis." (PMID 16507178, 2006). "In murine arthritis models and human RA synovium, CD8+ TRM cells persist in previously inflamed sites during remission and recruit circulating effector cells via the chemokine (C-C motif) ligand 5 (CCL5) axis, triggering arthritis flare-ups—a phenomenon termed “lesion memory”." (PMID 41462958, 2025). "For instance, monomeric mutant CCL2, but not CCL5 mutant (44AANA47), ameliorated arthritis in AIA rats." (PMID 36860872, 2023). "An amino-terminal-modified methionylated form of CCL5 (Met-RANTES) antagonized the binding of CCL3 and CCL5 to their receptors CCR1 and CCR5, respectively, and the blockade inhibited arthritis in AIA rats via the suppression of neutrophil and macrophage migration into the joints." (PMID 36860872, 2023).
Arthritis (continued). "Both IL-1β-induced synovitis and intra-articular lavage resulted in transient joint inflammation with elevations in synovial fluid TP, WBC count, and PGE2; however, increases in TNF-α and inflammatory chemokines CCL2, CCL3, CCL5, and CCL11 were predominantly restricted to synovitis joints only." (PMID 33980227, 2021). "Other resolutive chemokines (RANTES/CCL5, MIP2/CXCL2, MDC/CCL22), and cytokines IL-1RA and IL-10 were quantified in SuperMApo and thus added to recombinant TGF-β (all in similar quantity than measured in SuperMApo) to treat arthritis." (PMID 30542342, 2018). "No other arthritis-related cytokines [IL-1β, TNF, IL-17, interferon-γ, IL-4, CCL5 (also called RANTES, for regulated on activation, normal T cell expressed and secreted) and GM-CSF] could be detected in the serum (data not shown)." (PMID 26081345, 2015).